HNF1B (HNF1 homeobox B)
Diseases named in the same sentence as HNF1B in open-access papers (continued):
Sharing a sentence is not in itself a finding about the gene and the disease.
type 2 diabetes (continued). "Heterozygous LoF of HNF1B [MIM: 189907] and 17q12 deletions cause renal cyst and diabetes (RCAD) [MIM: 137920], a severe disorder characterized by renal abnormalities and maturity-onset diabetes of the young." (PMID 38185688, 2024). "While FOXA2 has been shown to control mRNA levels of PDX1, HNF1A, and HNF4A, mutations in HNF1A, HNF1B, HNF4A, and PDX1 are known to cause maturity-onset diabetes of the young (MODY)." (PMID 39322760, 2024). "Although these findings are consistent with the potential occurrence of maturity-onset diabetes, they fail to uncover the mechanism by which HNF1B haploinsufficiency results in pancreatic hypoplasia." (PMID 34295307, 2021). "Type 2 diabetes risk alleles in PPARG (encoding peroxisome proliferator-activated receptor γ [PPARγ]) and HNF1B (encoding hepatocyte nuclear factor 1 homeobox B) lower the risk of prostate cancer." (PMID 32705315, 2020). "in the case of 22q11.21 deletion heart defects or 17q12 deletion maturity-onset diabetes of the young (MODY) due to deletions of HNF1B." (PMID 29527097, 2018). "For example, several GWAS loci for type 2 diabetes contain genes known to harbour causal coding variants for rare Mendelian syndromes related to type 2 diabetes (e.g. HNF1A, HNF1B, WFS1, PPARG, KCNJ11, HNF4A, GCK)." (PMID 26702037, 2015). "The utility of routine biochemical biomarkers such as hsCRP or antibodies have been investigated for distinguishing several genetic etiologies (HNF1A, HNF4A, HNF1B) from Type 1 or Type 2 diabetes, or for distinguishing HNF1A specifically from Type 2 diabetes using HDL-cholesterol or hsCRP64–69." (PMID 37794142, 2023). "Variation in the P2 promoter of HNF4A, presumably leading to a decrease in HNF4A expression, has been associated with an increased risk of developing Type 2 diabetes, whilst bi-allelic inactivation of HNF1A and HNF1B has been shown to cause a number of types of cancer." (PMID 19787084, 2008). "The three related patients were reclassified as HNF1B-MODY after familial screening and had a previous diagnosis of type 2 diabetes." (PMID 36793123, 2023). "Our prediction identified the m6A genes HNF1B, HNF1A, WFS1, and IRS2 as the potential disease genes, which could provide a new clue to study the role of m6A in type 2 diabetes." (PMID 30601803, 2019).
prostate carcinoma (50 papers, 2010 to 2026). A carcinoma that arises from epithelial cells of the prostate gland. "As previously discussed, lower levels of HNF1B in prostate cancer has now been associated with higher EZH2, promoting EMT and metastasis." (PMID 33580750, 2021). "SNP rs4430796, in HNF1B, was strongly linked to prostate cancer risk and was one of the first loci to be identified for prostate cancer." (PMID 33580750, 2021). "Although this study was the first in associating HNF1B polymorphisms with prostate cancer risk in Korean men, the statistical significance of the SNPs was limited due to the small sample size." (PMID 33580750, 2021). "HNF1B is associated with cancer cell proliferation, tumour progression, and castration‐resistant prostate cancer." (PMID 33580750, 2021). "A fine‐mapping study in European ancestry indicated the role of five SNPs (rs4430796, rs4794758, rs3094509, rs7405696 and rs1016990) as the best predictors for prostate cancer risk in HNF1B gene loci." (PMID 33580750, 2021). "Logistic regression analysis in Korean patients (240 prostate cancer subjects and 223 controls) to evaluate the effects of 47 SNPs in HNF1B on prostate risk." (PMID 33580750, 2021). "DDR1 expression is one of twelve genes identified in a study to be associated with HNF1 homeobox B (HNF1b) mediated prostate cancer risk." (PMID 32492656, 2020). "Previous study in prostate cancer also showed that HNF1B promoter methylation correlates with prostate cancer risk SNP genotype and HNF1B expression." (PMID 31636385, 2020). "The rs8064454, a previously reported susceptibility loci for prostate cancer, is located in the intron of HNF1B at chromosome 17q12." (PMID 32010612, 2019). "In a recent GWAS, rs4430796 and rs7501939 in HNF1B were associated with the risks of both endometrial cancer in women of European background and prostate cancer." (PMID 30053805, 2018). "HNF1B is strongly associated with the risks of many cancers, including prostate cancer,ovarian cancer,endometrial cancer and lung cancer." (PMID 30053805, 2018). "All 15 publications were included in the evaluation of the association between the HNF1B rs4430796 and prostate cancer (Allelic associations: 1)." (PMID 30053805, 2018). "Several studies examined the associations between HNF1B and prostate cancer and endometrial cancer across various populations." (PMID 30053805, 2018). "Six publications were included in the evaluation of the association between the HNF1B rs7501939 and prostate cancer." (PMID 30053805, 2018). "Two publications included data regarding the association between the HNF1B rs11649743 and prostate cancer." (PMID 30053805, 2018). "Three publications were included in the evaluation of the association between the HNF1B rs3760511 and prostate cancer." (PMID 30053805, 2018). "Using gene set enrichment analysis (GSEA) we compared the 210-gene signature associated with HNF1B over-expression in vitro, with gene expression data from five clinical prostate cancer studies, to identify key genes related to functional phenotypes observed." (PMID 27732966, 2016). "This SNP was subsequently associated with PSA levels in unaffected men, as were other prostate-cancer related SNPs in the hepatocyte nucleartor-1 β (HNF1B) and β-microseminoprotein (MSMB) genes." (PMID 26431041, 2015). "Recently, a large study has shown that an HNF1β sequence variant confers an increased prostate cancer risk." (PMID 26464794, 2015). "In this study, the best model for prostate cancer risk in the HNF1β region included five SNPs, rs4430796, rs7405696, rs4794758, rs1016990 and rs3094509, and these SNPs together capture more of the risk associated with this region." (PMID 26464794, 2015). "For example, in prostate cancer the signal is explained by a five-SNP haplotype that includes SNPs from two peaks of association in HNF1B intron 2 (lead SNP rs4430796) and intron 4 (lead SNP rs4794758)." (PMID 25378557, 2015).
prostate carcinoma (continued). "Differential expression of HNF1B has been associated with prostate cancer recurrence and differential expression of HNF1B isoforms has been found in normal prostate and prostate cancer tissues." (PMID 22299039, 2012). "Here we present the results of a large collaborative meta-analysis of HNF1B, rs4430796 and rs7501939, which have the most consistent associations with both prostate cancer and T2D." (PMID 20526366, 2010). "The HNF1B gene, which encodes three isoforms, HNF1B(A), HNF1B(B) and HNF1B(C), in humans, demonstrates a similar alteration to the relative balance of alternatively expressed isoforms associated with cancer of the prostate." (PMID 20569440, 2010). "Even within the analyzed Caucasian-descent populations, we observed some modest between-study heterogeneity in the strength of the association between the HNF1B variants and prostate cancer." (PMID 20526366, 2010). "Expression of HNF1B is also associated with the development of BPH or prostate cancer." (PMID 38778357, 2024). "Interestingly, three HNF1B associated SNPs, rs11649743, rs4430796, and rs7501939, occurring in the intronic regions of HNF1B, were associated with decreased risk of prostate cancer by GWAS." (PMID 31636385, 2020). "In recent years, the results of genome‐wide association studies (GWAS) and fine‐mapping analysis have found that several different variants in the HNF1B gene are associated with the genetic risk of prostate cancer, which suggest that HNF1B has potential roles in prostate cancer progression." (PMID 33174391, 2020). "The changes in localization of paxillin within the cell together with alterations in migration potential and prominent clustering at the cell periphery when HNF1B is over-expressed in prostate cancer models strongly suggest that loss of HNF1B expression has a fundamental role in EMT." (PMID 27732966, 2016). "The results indicated that the prostate cancer risk role of HNF1β could possibly be associated with modulating the relationships between androgenic hormone and prostate cancer." (PMID 26464794, 2015). "Multiple independent HNF1B associations have now been reported for the lead SNPs in prostate cancer (in introns 1 and 4), while associations are limited to a single peak in intron 3 for the serous ovarian cancer subtype, and a single peak in intron 1 for the clear cell ovarian cancer subtype." (PMID 25378557, 2015). "Recently, it has been shown that the expression of HNF1β is associated with cancer risk in several tumors, including hepatocellular carcinoma, pancreatic carcinoma, renal cancer, ovarian cancer, endometrial cancer, and prostate cancer." (PMID 26464794, 2015). "In prostate cancer, the studies of HNF1β focus mainly on the single nucleotide polymorphisms." (PMID 26464794, 2015). "A definitive answer on whether HNF1B variants modulate also the risk of other malignancies, or show specificity for prostate cancer, requires large sample sizes." (PMID 20526366, 2010). "HNF1B is a transcription factor expressed in a limited number of tissues, and has previously been associated with renal and ovarian tumours as well as prostate cancer." (PMID 20569440, 2010). "An interesting observation has been that specific variants in the HNF1B gene (formerly TCF2) have been demonstrated to be associated both with the risk of prostate cancer and the risk of T2D with the effects being in the opposite direction for these two phenotypes." (PMID 20526366, 2010). "To date, GWAS for endometrial cancer have convincingly identified evidence for endometrial cancer risk association at the HNF1B locus, the risk allele of which (rs4430796A) maps to a region that has also been associated with the risk of ovarian and prostate cancers." (PMID 25487306, 2015). "A previous study reported that HNF1B functions as a tumor suppressor and inhibits cell proliferation in prostate cancer." (PMID 39915461, 2025).
prostate carcinoma (continued). "For example, MTNR1B rs10830963 and HNF1B rs757210, as T2D-related genes, have inhibitory effects on prostate cancer." (PMID 40760716, 2025). "Together these studies highlight the transcriptional role of HNF1B and its network in prostate cancer, although extensive studies on its mechanism are required to interpret its role in disease." (PMID 33580750, 2021). "Once methylated, the activity of HNF1B as a tumour suppressor is lost in course to the development of prostate cancer." (PMID 33580750, 2021). "A study understanding the regulation of the UDP glucuronosyltransferase 2B17 gene promoter found elevated expression of this gene by HNF1B in LNCaP prostate cancer cell line." (PMID 33580750, 2021). "Forced expression of SMAD6 completely mitigated HNF1B‐mediated cell growth inhibition of DU145 prostate cancer cells." (PMID 33174391, 2020). "In the present study, we demonstrate that HNF1B inhibits prostate cancer cell proliferation by suppressing Cyclin D1 expression." (PMID 33174391, 2020). "Our results revealed a new mechanism of HNF1B in prostate cancer development, and provided new understanding of the signalling regulation network of disease progression." (PMID 33174391, 2020). "Although the study was based on RNAi and overexpression approaches, our findings call for future investigation of EZH2 inhibitors in treating tumors, including prostate cancer, with low HNF1B expression mediated by EZH2 overexpression." (PMID 31636385, 2020). "In summary, we provide the novel mechanisms and evidence in support HNF1B as a tumour suppressor gene for prostate cancer." (PMID 33174391, 2020). "Until recently, HNF1B was reported to function as a tumor suppressor in renal, ovarian, endometrial, colorectal, breast, and prostate cancers." (PMID 31636385, 2020). "Overexpression of HNF1B in prostate cancer cells led to the arrest of G1 cell cycle and decreased Cyclin D1 expression." (PMID 33174391, 2020). "Taken together, we have established a previously underappreciated axis of EZH2-HNF1B-SLUG in prostate cancer, and also provide evidence supporting HNF1B as a potential prognosis marker for metastatic prostate cancer." (PMID 31636385, 2020). "HNF1B overexpression resulted in a decreased proportion of cells in S phase, which indicated that HNF1B suppressed prostate cancer cell proliferation by influencing cell cycle through G1‐phase cell cycle arrest." (PMID 33174391, 2020). "As expected, overexpression of Cyclin D1 successfully mitigated HNF1B‐mediated cell growth inhibition of DU145 prostate cancer cells." (PMID 33174391, 2020). "In this study, we found that the overexpression of HNF1B in prostate cancer cells can inhibit cell growth and lead to G1 cell cycle arrest through in vivo and in vitro experiments." (PMID 33174391, 2020). "Microarray based expression analyses using GSE35988 and GDS1439 datasets indicated significant reduced HNF1B expression in metastatic prostate cancer samples." (PMID 31636385, 2020). "Our study for the first time determined the role of RBBP7 as a corepressor associated with the tumor suppressor HNF1B to repress SLUG expression and EMT phenotype in prostate cancer." (PMID 31636385, 2020). "Then, we detected the colony formation ability after HNF1B overexpressing in prostate cancer cell lines." (PMID 33174391, 2020). "All these data above indicate that HNF1B suppresses the proliferation of prostate cancer cells by inhibiting the expression of Cyclin D1." (PMID 33174391, 2020). "Taken together, our data suggest that the role and mechanisms of HNF1B in prostate cancer proliferation make it a potential therapeutic target of this highly aggressive tumour." (PMID 33174391, 2020). "Then we did immunohistochemistry and found significant reverse correlation between HNF1B and Cyclin D1 protein levels in metastatic prostate cancer tissues." (PMID 33174391, 2020).
prostate carcinoma (continued). "After 7‐day observation, we found that the clonogenic ability of prostate cancer cells was suppressed in HNF1B overexpressed PC‐3 cells, which was also consistent with our previous results in DU145." (PMID 33174391, 2020). "HNF1B suppresses EZH2‐mediated migration of two prostate cancer cell lines via represses the EMT process by inhibiting SLUG expression." (PMID 33174391, 2020). "Our previous studies showed the preliminary function of HNF1B in prostate cancer proliferation and migration as a potential tumour suppressor gene." (PMID 33174391, 2020). "All these data together demonstrated that SMAD6 is a direct target of HNF1B in the regulation of Cyclin D1 expression and cell growth of prostate cancer cells." (PMID 33174391, 2020). "In mechanism research, we determined that HNF1B inhibits prostate cancer cell proliferation by down‐regulating the expression of Cyclin D1." (PMID 33174391, 2020). "To further confirm the effect of HNF1B in prostate cancer cell proliferation, we overexpressed HNF1B in PC‐3 cells and knocked down HNF1B in both PC‐3 and DU145 cells." (PMID 33174391, 2020). "To dig out how HNF1B represses prostate cancer cell proliferation, we analysed cell cycle of HNF1B OE DU145 cell." (PMID 33174391, 2020). "HNF1B can inhibit the EMT process of prostate cancer cell via suppression of SLUG expression, resulting in the inhibition of distant metastasis." (PMID 33174391, 2020). "To further confirm the correlation between HNF1B and Cyclin D1 expression in prostate cancer samples, we first analysed online publicly available data sets from TCGA data set and GSE21032." (PMID 33174391, 2020). "Recent studies have shown that HNF1B has a significant correlation with the occurrence and development of various tumors, such as prostate cancer and pancreatic cancer 21,22." (PMID 33173410, 2020). "We also discover the critical role of HNF1B in prostate cancer cell growth, but the molecular mechanism by which is still not clear." (PMID 33174391, 2020). "In our previous study, we have shown that HNF1B can diminish the effect of EZH2 in promoting prostate cancer proliferation." (PMID 33174391, 2020). "HNF1B is previously reported to act as a tumor suppressor in several tumors, including renal cancer, ovarian cancer, and prostate cancer." (PMID 32925947, 2020). "Gene ontology (GO) enrichment analysis of the DEG following over-expression of HNF1B in this prostate cancer model suggested that biological pathways in cellular movement, growth and proliferation were over-represented." (PMID 27732966, 2016). "TCGA prostate cancer methylation data further confirm elevated HNF1B promoter methylation in tumor compared to normal tissue." (PMID 27732966, 2016). "The mRNA sequencing analysis also reveals that several genes, such as NUDT11, CCNA1, and HNF1B, known to promote prostate cancer progression, are significantly up-regulated in the CIC knock-down PC-3 cells." (PMID 26124181, 2015). "The ratio of HNF1B(B):HNF1B(C) isoforms changes from 0.7 [IQR 0.22]: 1 in BPH to 35.4 [IQR 124.71]: 1 in prostate cancer tissues (P = 2.9 × 10-9)." (PMID 20569440, 2010). "In prostate cancer tissues however, isoform HNF1B(B) is predominant at 95% total HNF1B expression, with the levels of HNF1B(C) dropping to only 3%." (PMID 20569440, 2010). "Since we only included the genes which have significant associated eQTLs in the GTEx prostate tissue summary data, some previous reported genes in prostate cancer risk were not included in our analysis, such as HNF1B." (PMID 38887957, 2024). "For example, in our gene‐prostate cancer example, we did not include HNF1B due to the lack of significant eQTL‐HNF1B pairs existing in GTEx prostate tissue, although this gene has been strongly implicated gene for expression in prostate cancer risk." (PMID 38887957, 2024). "However, in prostate cancer tissues HNF1B(B) isoform contributed to 95% of the total HNF1B expression." (PMID 33580750, 2021).